RN7SL502P (RNA, 7SL, cytoplasmic 502, pseudogene)
Gene: Miscellaneous RNA gene on chromosome 6 (36,450,912 to 36,451,201, reverse strand). Ensembl gene ENSG00000240733.
Homologues: Orthologues: chimpanzee Metazoa_SRP (99% identical), macaque Metazoa_SRP (89% identical), guinea pig Metazoa_SRP (57% identical). Paralogues in human: RN7SL2 (82% identical), RN7SL1 (81% identical), RN7SL122P (81% identical), RN7SL3 (80% identical), RN7SL126P (80% identical), RN7SL732P (79% identical), RN7SL177P (79% identical), RN7SL186P (79% identical), RN7SL444P (79% identical), RN7SL45P (79% identical), RN7SL408P (79% identical), RN7SL679P (79% identical), and 702 more.